ALB (albumin)
Diseases named in the same sentence as ALB in open-access papers (continued):
Sharing a sentence is not in itself a finding about the gene and the disease.
Thrombocytopenia (continued). "Five (50%) patients had thrombocytopenia, two (20%) patients had slightly elevated bilirubin, and almost all patients had decreased albumin, reflecting the complexity of disease management in maternal patients." (PMID 35047527, 2021). "Other laboratory data showed thrombocytopenia (n = 43,000) at the time of admission but other tests were in normal limits (leukocytes: 5.1 × 103/μL, Na: 142, K: 4.4, Ca: 9.4, Albumin: 3.4, and Mg: 2.1)." (PMID 33726699, 2021). "The most common reasons for trial ineligibility in both analyses were low albumin or prealbumin levels (2281 patients [15.5%]), thrombocytopenia (1369 patients [9.3%]), and elevated bilirubin levels (1293 patients [8.8%]) (eFigure 4 in the Supplement)." (PMID 33416886, 2021). "This includes renal impairment, elevated liver function tests, serum albumin levels, thrombocytopenia, and leukocytopenia." (PMID 32413028, 2020). "Thrombocytopenia, worsened respiratory condition, and decreased coagulation function were observed, and she received treatment with albumin, fresh frozen plasma, and diuretics." (PMID 32749073, 2020). "Elevations of amylase, lipase, and liver enzymes levels, low serum albumin level, and thrombocytopenia were observed." (PMID 32181028, 2020). "Factors associated with liver-related morbidity included lower serum albumin concentration, thrombocytopenia, prolonged prothrombin time as measured by INR, and higher ICG R15 value." (PMID 33152023, 2020). "A significant increase in the SOFA scores (p < 0.001), incidence of acidosis, episodes of hypotension, thrombocytopenia, and CRP concentrations were associated with decreases in the serum albumin levels." (PMID 30423847, 2018). "More prominent signs of clinical manifestations and hematology findings commonly found in DHF, such as the hemoconcentration, thrombocytopenia, elevated liver enzymes and albumin, were observed in children with DHF." (PMID 28575000, 2017). "The patient with the Child-Pugh score of 7 had also a serum albumin < 35 g/l and a thrombocytopenia < 100,000/μl." (PMID 24884400, 2014). "It usually presents clinically as angioma with thrombocytopenia and low fiber albumin, namely thrombocytopenic purpura syndrome (Kasabach-Merritt syndrome, KMS)." (PMID 23420140, 2013). "For the period of hospital admission, the blood urea nitrogen level, the serum creatinine concentration, and blood leukocyte counts were greatly elevated, whereas the serum albumin level decreased, and most of the patients underwent the thrombocytopenia." (PMID 23091554, 2012). "Laboratory findings that significantly predicted mortality by univariate analysis were albumin level, thrombocytopenia, and PaO2/FiO2." (PMID 21535895, 2011). "Mortality was also higher for patients with reduced serum albumin values, thrombocytopenia, and immature leukocyte more than 10%(p = 0.036, and 0.008, and 0.015, respectively)." (PMID 21208438, 2011). "In turn, fragments of platelets conjugated with serum albumin represent a future possibility for dispensing with platelet infusion in cases of thrombocytopenia." (PMID 18573217, 2008). "Univariate and stepwise multivariate logistic regression analyses identified lower albumin and higher alanine aminotransferase (ALT), alkaline phosphatase, and total bilirubin levels as independent factors significantly associated with thrombocytopenia risk (OR=1.95~6.60)." (PMID 40510350, 2025). "Although the CT severity score was developed solely based on imaging findings, it demonstrated moderate to strong correlations with laboratory markers of inflammation (white blood cell count), thrombocytopenia (platelet count), and proteinuria (uPCR, albumin, and total protein)." (PMID 40072771, 2025). "This study aimed to evaluate the diagnostic performance of current fibrosis assessment methods and develop a novel, simplified scoring system—the Aspartate Aminotransferase (AST)-Thrombocytopenia-Albumin (ATA) score—to enhance ease of use and clinical applicability." (PMID 40361937, 2025).
Thrombocytopenia (continued). "In addition to ALT, our observational study also identified TBIL, ALB, and ALP as independent factors significantly associated with the risk of thrombocytopenia." (PMID 40510350, 2025). "Symptoms include nausea, vomiting, abdominal pain, oropharyngeal ulcers, respiratory distress, decreased urine, altered sensorium, leukocytosis, thrombocytopenia, transaminitis, increased serum total bilirubin, low serum albumin, and a rise in serum creatinine." (PMID 41384173, 2025). "Compared to paclitaxel, albumin-bound paclitaxel (nab-paclitaxel) demonstrates superior efficacy in the treatment of esophageal cancer, with fewer adverse reactions such as diarrhea, thrombocytopenia, and musculoskeletal pain." (PMID 40900779, 2025). "Clinical pathology changes included reductions in red cell parameters (RBC count, hemoglobin concentration, and hematocrit), thrombocytopenia, prolonged coagulation parameters (PT and aPTT), and acute phase reactions (ie, decreased albumin and increased globulin, increased fibrinogen)." (PMID 38343535, 2024). "Among the parameters analyzed, our study demonstrated thrombocytopenia, decreased leukocytes count with neutropenia, lymphocytosis and monocytosis, elevated SGPT and SGOT, increased urea and decreased albumin, increased prothrombin time to be significantly associated with dengue-positive cases." (PMID 39741523, 2024). "In the univariate analysis of patients including the PALBI grade, thrombocytopenia, lower albumin levels, higher creatinine levels, ascites, AFP > 200 ng/mL, vascular invasion, larger tumor size, performance status 2 and PALBI grades 2–3 were associated with decreased long-term survival." (PMID 37046586, 2023). "In the univariate analysis of patients including the PAL grade, thrombocytopenia, lower albumin levels, higher creatinine levels, ascites, AFP > 200 ng/mL, vascular invasion, larger tumor size, performance status 2 and PAL grades 2–3 were associated with decreased survival." (PMID 37046586, 2023). "In multivariate analysis, thrombocytopenia (HR: 2.81, 95% CI, 1.6-5, P < 0.001), low serum albumin (HR: 2.49, 95% CI, 1.44-4.3, P = 0.001) and a PFS >12 months at index anti-CD38 therapy (HR: 0.367, 95% CI, 0.181-0.745, P = 0.006) were the only independent prognostic factors for OS." (PMID 37936678, 2023). "In the univariate analysis of patients including the MELD score, thrombocytopenia, lower albumin levels, higher creatinine levels, ascites, AFP > 200 ng/mL, vascular invasion, larger tumor size, performance status 2 and MELD score > 8 were associated with decreased long-term survival." (PMID 37046586, 2023). "Severely affected elephants presented with thrombocytopenia, depletion of monocytes, lymphocytes and heterophils, a monocyte:heterophil (M:H) ratio lower than 2.37, hypoproteinemia (both albumin and globulin), severe grade of heterophil toxicity, and low red blood cell counts and pack cell volumes." (PMID 34511026, 2021). "We found many parameters (lower albumin, splenectomy, thrombocytopenia, elevated LDH, higher b2-microglobulin, and HBsAg positivity) to be associated with overall survival, but albumin was the only parameter to retain marginal significance in multivariate analysis." (PMID 31630512, 2020). "Respiratory rate, crackles, hepatomegaly, creatinine, AST, ALT, alkaline phosphatase, albumin, hemoglobin, thrombocytopenia (150 × 109/L), plateletcrit ≤0.19, and MPV >7.9, and abnormal chest radiograph were able to significantly predict MODS on univariate logistic regression analysis." (PMID 32802052, 2020). "Thrombocytopenia, a raised C-reactive protein level, a low albumin level, and elevated hepatic enzyme levels (particularly AST) were common findings; the latter was shown previously to be useful for differentiating scrub typhus from other causes of undifferentiated fever, such as dengue, in adults." (PMID 30864670, 2020).
Thrombocytopenia (continued). "DS treatment neither caused adverse events, particularly bleeding or thrombocytopenia, nor induced significant changes in serum albumin, total bilirubin, prothrombin time, and residual liver function." (PMID 29070023, 2017). "Similar results were obtained when frequencies of each individual sign were compared, except for the rates of thrombocytopenia and albumin/globulin ratio inversion that were found significantly higher in dogs of combined A–C studies (p = 0.009 and p = 0.011, respectively)." (PMID 23675551, 2013). "Moreover, other predictors of fatality included higher interleukin-10, lower albumin, and higher lactate dehydrogenase levels in serum, as well as central nervous system involvement and/or presence of thrombocytopenia, but also persistent hyperferritinaemia during the time of treatment." (PMID 40572665, 2025). "Studies have shown that patients receiving human serum albumin therapy during Linezolid treatment have a low incidence of thrombocytopenia, and there is a significant negative correlation between serum albumin concentration and Linezolid-induced thrombocytopenia." (PMID 38449807, 2024). "On univariate analysis, older age, low albumin (Alb) level at baseline, low PLT count at baseline, induction chemotherapy, and intravenous oxaliplatin chemotherapy every three weeks were statistically significantly associated with increased risks of grade 2+ thrombocytopenia." (PMID 38230393, 2023). "Elevated LDH level, multiple anatomical sites of skin involvement, thrombocytopenia and lower albumin level may be risk factors for poorer prognosis of non-MF/SS CTCLs." (PMID 31978091, 2020). "Elevated serum lactate dehydrogenase level, thrombocytopenia, multiple anatomical sites of skin involvement and lower albumin level may be associated with poor prognosis in non-MF/SS CTCLs, but the latter two were not in CBCLs." (PMID 31978091, 2020). "Independent factors associated with in-hospital mortality were age ≥60 years, CWIC score, qSOFA score at the time of hospitalization, admission WBC, serum albumin, AST, lymphocytopenia, and thrombocytopenia at the time of admission." (PMID 33759606, 2021). ", higher CWIC score, higher qSOFA score, higher WBC counts on admission, lower albumin on admission, elevated AST, lymphocytopenia, and thrombocytopenia on admission." (PMID 33759606, 2021). "On admission, 149 (32.04%) patients had leukocytopenia, 78 (16.77%) had lymphocytopenia, five (1.08%) had thrombocytopenia, 69 (14.84%) had increased international normalized ratio (INR), and 170 (36.56%) had decreased albumin level." (PMID 32397011, 2020). "The most common treatment-related adverse effect of pm-Pac is myelosuppression, particularly neutropenia and thrombocytopenia, which is not significantly different from that of albumin-paclitaxel." (PMID 41560075, 2026). "Higher white blood cell count and older age emerge as the most consistently validated predictors, followed by increased IRB/BICcreatinine, low albumin, thrombocytopenia, and coagulopathy, although their predictive value is not uniform across studies." (PMID 41440532, 2025). "The FLC levels correlated significantly also with urinary albumin excretion but not with the extent of thrombocytopenia or with the level of inflammation as indicated by maximum level of blood leukocyte count or maximum interleukin (IL)-6." (PMID 34379707, 2021). "Many prognostic factors have been described for SMZL, such as leukocytosis, thrombocytopenia, elevated β2-microglobulin, anemia, elevated lactate dehydrogenase (LDH), decreased albumin, impaired performance status, advanced age, bone marrow involvement, and histologic transformation." (PMID 31630512, 2020). "The etiology of thrombocytopenia is likely multifactorial in the setting of infection including consumptive coagulopathy, disseminated intravascular coagulation (DIC) and is likely a marker of severe disease and organ dysfunction along with albumin." (PMID 32983698, 2020).
Thrombocytopenia (continued). "The patients showed characteristic clinical symptoms (sudden onset of flu-like symptoms), impairment of laboratory parameters (thrombocytopenia, rise in levels of serum creatinine, leukocytes, LDH, CRP, and low levels of serum albumin), proteinuria, and hematuria." (PMID 30541481, 2018). "The univariate analysis demonstrated that five clinical factors were associated with PFS and OS (P < 0.1); these factors were increased LDH level, thrombocytopenia, low serum albumin level, high serum β2-microglobulin and non-CR after front-line treatment." (PMID 29108331, 2017). "Univariate analysis revealed that nephritis, active lupus, thrombocytopenia, leukopenia, hypocomplementemia, low serum albumin level, aPL positive, ANA positive, and non-use of hydroxychloroquine (HCQ) were associated with pregnancy loss." (PMID 28441446, 2017). "In addition there was a correlation of IaIp with thrombocytopenia (P = 0.002), anti-thrombin III (ATIII, P = 0.024) and albumin levels (P = 0.018)." (PMID 20386596, 2010). "Thrombocytopenia (94.1%), elevated liver marker (aspartate aminotransferase [AST] >40 IU/L, 91.2%; alanine aminotransferase [ALT] >40 IU/L, 58.5%) and lactate dehydrogenase levels (LDH) (100%), and decreased albumin levels (76.5%) were the common laboratory abnormalities observed." (PMID 39481131, 2025). "Albumin infusion (P = 0.002), glucocorticoid use (P < 0.001), and antiviral drug use (P = 0.010) were significantly higher in the patients with thrombocytopenia than in those without thrombocytopenia." (PMID 37560317, 2023). "Finally, updated clinical scores incorporating BUN, seizures, and albumin levels may provide more accurate triage tools during DENV-3 outbreaks, particularly when classical warning signs (like thrombocytopenia) are absent." (PMID 40733567, 2025).
atrial fibrillation (174 papers, 2012 to 2026). A disorder characterized by an electrocardiographic finding of a supraventricular arrhythmia characterized by the replacement of consistent P waves by rapid oscillations or fibrillatory waves that vary in size, shape and timing and are accompanied by an irregular ventricular response. "After a series of rigorous MR analyses, we consistently found a significant causal relationship between the increase in serum albumin levels and the reduction in the risk of atrial fibrillation." (PMID 38655495, 2024). "The identified predictors included age, preoperative serum albumin level, nutritional risk screening, atrial fibrillation, COPD, FEV1/FVC, and the surgical approach." (PMID 38965472, 2024). "For instance, consider a patient with an FEV one-second rate of 83%, absence of chronic obstructive pulmonary disease, laparoscopic surgery, atrial fibrillation, preoperative serum albumin 28 g/L, age 64, and nutritional risk." (PMID 38965472, 2024). "In view of this, we urgently need to conduct more in-depth research to clarify the causal relationship between serum albumin levels and atrial fibrillation and its underlying mechanisms." (PMID 38655495, 2024). "Of particular concern is the strong association between low albumin levels measured during the acute phase and an increased risk of atrial fibrillation in clinical conditions characterized by increased oxidative stress, such as ischemic stroke." (PMID 38655495, 2024). "The analysis showed that compared to patients with low serum albumin levels, patients with high serum albumin levels had a significantly reduced risk of developing atrial fibrillation (OR: 0.62, 95% CI: 0.44–0.89, P = 0.009)." (PMID 38655495, 2024). "Our study is the first to fully utilize publicly available GWAS datasets for in-depth MR analysis, aiming to reveal the direct causal link between serum albumin level and atrial fibrillation." (PMID 38655495, 2024). "We further analyzed the exposure factor of serum albumin and selected 26 serum metabolites previously identified as having genetic causal relationships with atrial fibrillation as outcome variables for in-depth analysis." (PMID 38655495, 2024). "Specifically, a decrease in albumin levels is associated with an 11% increase in the risk of atrial fibrillation within 30 days of its occurrence." (PMID 38655495, 2024). "In summary, our study strongly demonstrates the causal relationship between serum albumin and reduced risk of atrial fibrillation through genetic methods, and reveals the key mediating role of two serum metabolites in this relationship." (PMID 38655495, 2024). "Specifically, Docosatrienoate levels played a mediating role in the causal relationship between serum albumin and atrial fibrillation, with a magnitude of effect of β = −0.008, SE = 3.271e-05, and a 95% confidence interval ranging from −0.008 to −0.007." (PMID 38655495, 2024). "The analysis results showed that there was a significant association between the increase in serum albumin levels and the reduction in the risk of atrial fibrillation (IVW: Beta = −0.172, OR = 0.842, 95% CI: 0.753–0.941, P = 0.002)." (PMID 38655495, 2024). "This study strongly demonstrates the causal relationship between serum albumin and reduced risk of atrial fibrillation through genetic methods, and reveals the key mediating role of two serum metabolites in this relationship." (PMID 38655495, 2024). "While RDW and albumin have been shown to be associated with an increased risk of atrial fibrillation, RAR, serving as a composite marker, exhibits a superior predictive effect." (PMID 38515030, 2024). "Previously, no study has used MR analysis to clarify the causal relationship between serum albumin level and the risk of atrial fibrillation." (PMID 38655495, 2024).